STAT3 (signal transducer and activator of transcription 3)
Diseases named in the same sentence as STAT3 in open-access papers (continued):
Sharing a sentence is not in itself a finding about the gene and the disease.
tumor (continued). "Immunoblotting analysis of tumor tissue demonstrated a significant decrease in STAT3 phosphorylation in the high-concentration VaM, doxorubicin alone, and combination treatment groups." (PMID 37569363, 2023). "STAT3 signaling has both, tumor-suppressive and oncogenic roles in specific tissue contexts and is implicated in the regulation of malignant transformation and metastatic dissemination." (PMID 37573301, 2023). "Further in vivo studies showed that anti-CD19-STAT3 siRNA conjugate significantly reduced tumor progression with decreased STAT3 activity, suggesting potential utilization for cancer treatment." (PMID 37686472, 2023). "The functions of DC, T cells, natural killer (NK) cells, and neutrophils are significantly enhanced in tumor-bearing mice with Stat3−/− hematopoietic cells." (PMID 36911202, 2023). "In several malignant tumors, STAT3 activation is related to tumor metastasis, invasion, proliferation, and acquisition of tolerance to chemotherapy and radiotherapy." (PMID 36961655, 2023). "Inhibit STAT3-mediated gene regulation, block tumor cell proliferation and selectively induce apoptosis of tumor cells with activated STAT3." (PMID 37057285, 2023). "Nevertheless, few studies have examined the relationship between tumor progression and STAT3 activation in SCLC." (PMID 36961655, 2023). "The IL-6/JAK/STAT3 pathway is aberrantly over-activated in many types of cancer and drives tumor cell proliferation, survival, invasion, and metastasis, while it strongly suppresses antitumor immune responses." (PMID 37835536, 2023). "Studies have also confirmed that Ginsenoside Rg3 (Rg3) can effectively reduce the incidence of tumor cell stemness and the EMT by depleting MDSCs in the tumor and downregulating the STAT3 pathway." (PMID 37857728, 2023). "The subsequent increase in STAT3 activity increased migration and invasion of cells replated from suspension cultures in vitro, while knockout of STAT3 prevented the formation of tumours in vivo." (PMID 37181747, 2023). "Tumor-associated macrophage (TAM)-derived IL-6 is involved in small-cell lung cancer (SCLC) progression and chemoresistance via the activation of signal transducer and activator of transcription 3 (STAT3) in the tumor microenvironment." (PMID 36961655, 2023). "Tumors of the pancreas, lungs, kidneys, esophagus, cervix, colon, and gastrointestinal tract benefit from aberrant STAT3 activity, which also enhances tumor cell survival and adds to the malignant phenotype." (PMID 36852795, 2023). "The significant difference between elevated concentrations of STAT5 and STAT3 in the cells treated with the studied compounds can be a reaction to stress, or the studied compounds affecting the Jurkat tumor culture are probably mitogen-like compounds." (PMID 36765714, 2023). "IL-11 promoted tumor progression by initiating gp130/Stat3 pathway through TLR2, and cancer metastasis was inhibited by blocking the TLR2 signal in mice." (PMID 37153547, 2023). "Passive accumulation in TME and precise binding of tLyp1 to NRP1 synergistically delivered imatinib into tumour‐infiltrating Treg cells, and their immunosuppressive properties were thwarted by inhibiting the phosphorylation of STAT3 and STAT5." (PMID 37403792, 2023). "STAT3, which promotes tumor growth and metastasis, was also significantly downregulated in PT-complex-treated cells." (PMID 38027033, 2023). "CDK9-mediated activation of STAT3 was inhibited in the tumor tissues in acetyl-bufalin-treated mice." (PMID 36903477, 2023). "Cucurbitacin D induces apoptosis and suppresses tumor cell proliferation by inhibiting signal transducer and activator of transcription 3 (STAT3) and phosphorylating NF-κB." (PMID 37138292, 2023). "Further, unchecked STAT3 activity facilitates tumor formation, and the overexpression of STAT3 is sufficient to transform 3T3 fibroblasts and induce tumor formation in different mouse models." (PMID 37190033, 2023).
tumor (continued). "Research has shown that astaxanthin can exert antitumor effects on tumor cells through the STAT3 pathway." (PMID 38031104, 2023). "Researches show that STAT3 is critical for tumor transformation downstream of oncogenes Src and Ras." (PMID 36911202, 2023). "The JAK/STAT3 signaling pathway is involved in almost all immune regulatory processes, including tumor cell recognition and tumor-driven immune escape." (PMID 37202657, 2023). "IL6 secreted by tumor cells can activate STAT3 signaling, inducing HIF-1⍺ and VEGF and conditioning lymphatic endothelial cells to express CCL5." (PMID 37440925, 2023). "CpG-STAT3ASO disrupts tumour-induced immunosuppression by inhibiting activity of STAT3 and stimulating TLR9 signaling in antigen presenting cells, such as DCs ang macrophages." (PMID 38259453, 2023). "ICAM-1 expressed on ECs is the key molecule for tumor cells to adhere to ECs and is induced via STAT3 activation." (PMID 37124539, 2023). "Tumor expression of AHR can result in an autocrine AHR-IL-6/STAT3 signaling loop via kynurenine, an immunosuppressive AHR agonist ligand produced by the metabolism of the essential amino acid tryptophan." (PMID 37511453, 2023). "They show very similar in vitro effects on STAT3 signaling, and consequently can be used for both tumor growth inhibition and modulation of immune responses to tumors and infectious agents." (PMID 37182134, 2023). "Apatinib can inhibit the VEGFR2/STAT3/Bcl-2 signaling pathway and increase the expression of beclin-1 in vivo, thereby inducing autophagy and apoptosis of tumor cells." (PMID 37124541, 2023). "Another SERM, bazedoxifene, was shown to have the function of inhibiting STAT3 phosphorylation and STAT3 DNA binding, inducing apoptosis, and suppressing tumor growth in PAAD cells with persistent IL6/GP130/STAT3 signaling." (PMID 36817451, 2023). "STAT3 is a tumor-promoting oncogene shown in several tumors and is intimately linked to inflammation and immunity." (PMID 37799727, 2023). "Honokiol, a herbal constituent that possesses various anti-tumor and anti-angiogenesis properties, was found to inhibit tumor sphere formation in oral CSC-like OSCC cells by impeding the JAK2/STAT3 pathway activity." (PMID 38170015, 2023). "As a transcription factor, STAT3 directly regulates the expression of oncogenes, thereby triggering tumor development." (PMID 36873736, 2023). "The regulation of numerous genes essential for tumor cell survival, proliferation, migration, and angiogenesis is attributed to STAT3." (PMID 37630387, 2023). "Intriguingly, we discovered that the expressions of MET, STAT3, and AKT were linked with the tumor stage using the web-based application GEPIA." (PMID 37373393, 2023). "We found that metformin treatment in a clinically relevant dose of ~ 70 μM decreased size, weight, and tumor volume in AR/STAT3 expressing 22Rv1 cells but was ineffective for PC3 xenografts, which lack STAT3." (PMID 37573301, 2023). "In summation, our comprehensive findings provided robust confirmation that STAT3 R729 methylation constituted an indispensable factor in PRMT6-mediated tumor metastasis." (PMID 37813837, 2023). "Recent studies have highlighted that tumor-intrinsic PD-L1 signaling can be modulated by STAT3, AKT, MET oncogenic pathway, epithelial–mesenchymal transition, or BIM expression." (PMID 36894581, 2023). "Among them, STAT3 is a transcription factor that has been generally studied in tumor and inflammation." (PMID 37716993, 2023). "CD36+CAF-derived MIF potentiated the capacity of MDSCs to promote immunosuppressive TME and tumor stemness via IL-6/STAT3 activation." (PMID 38065972, 2023).
tumor (continued). "Similar to the results in vitro, GYY4137 notably suppressed tumor growth in the model of subcutaneous HCC cells xenotransplantation through suppressing the activation of STAT3 and its downstream target gene expression in vivo." (PMID 37886126, 2023). "STAT3 has been confirmed to perform a tumor suppressive role in KRAS-driven lung tumorigenesis 25,26." (PMID 36993454, 2023). "According to the results of oncomine, the expression of STAT1 was increased and the expression of STAT3/5A/5B were decreased in tumor tissues compared with normal tissues." (PMID 36862902, 2023). "STAT3 played a role in several cross talk levels between tumor cells and the immune microenvironment, and mediated tumor‐induced immunosuppression." (PMID 37306187, 2023). "Its mechanism of action is complex, but blocking the JAK2/STAT3 signaling pathway appears to be responsible for its anti-tumor effects." (PMID 36902139, 2023). "The biological function of STAT1 and STAT3 differs in terms of cell growth and induction of an anti-tumor immune response." (PMID 37047709, 2023). "In a mouse Molm-16 xenograft model, it achieved significant degradation of STAT3 and complete and durable tumor regression." (PMID 37496997, 2023). "The best hits from screening these diversity sets, STND-11-20 were synthesized by Enamine and tested for STAT3-dependent tumor cell grows inhibition." (PMID 37182134, 2023). "Several studies have shown that application of STAT3 inhibitors to several tumor models has therapeutic effects." (PMID 36739406, 2023). "IHC staining and western blot were next performed to detect the phosphorylation levels of STAT3 in tumor tissues, and the results were consistent with the tumor growth curve." (PMID 37002206, 2023). "The systemic delivery of AZD9150 to mice bearing SUP-M2 tumors lowered the level of STAT3 protein in the tumor samples compared with the control." (PMID 38067351, 2023). "For example, STAT1 can suppress the growth and invasion of tumors, whereas STAT3 inhibits apoptosis and induces tumor cell proliferation and tumor-promoting inflammation." (PMID 37047709, 2023). "Meanwhile, inhibiting IL-6/STAT3 suppressed tumor cell growth and enhanced the sensitivity to antitumor drugs." (PMID 37404767, 2023). "Through the IL-6/STAT3/PD-L1 axis, CAFs modulated neutrophil activation, survival and function in tumour tissues in HCC to promote immune suppression." (PMID 37569598, 2023). "In contrast, STAT3 deletion in myeloid cells results in the generation of NK and cytotoxic T-cells that respond effectively and hinder tumor growth." (PMID 36672335, 2023). "STAT3 from tumour cells can reduce anti-tumour immunity by suppressing MICA and generating pro-inflammatory chemokines." (PMID 37784183, 2023). "Many small-molecule inhibitors of JAKs, or STAT TFs, especially JAK2 and STAT3, have been assessed for their anti-tumor activity in GBM." (PMID 37947625, 2023). "Activation of NF-κB and STAT3 pathways enhances tumor infiltration of M1/M2-like macrophages and Treg cells, thereby increasing tumor growth and metastasis in RCC." (PMID 37190141, 2023). "Under the stimulation of oncogenic signals, STAT3 is continuously activated, is constitutively expressed in the nucleus in an activated state, continuously activates target genes, and promotes tumor cell growth." (PMID 37006252, 2023). "For example, it was reported that tumor growth is reduced in IL17-/- mice, probably due to the lost capacity of IL-17 to promote tumor growth via the IL-6/STAT3 pathway." (PMID 37460545, 2023). "The molecular mechanisms suggested that TMTC3 facilitated tumor angiogenesis by regulating Rho GTPase/STAT3/VEGFA pathway mediated by interacting with IMPDH2 Bateman domain." (PMID 37752569, 2023). "In NSCLC, poor prognosis and chemotherapy resistance were found to be related to the persistent activation of STAT3, and the inhibition of STAT3 activity can effectively inhibit tumor progress 11-13." (PMID 37928418, 2023).
tumor (continued). "In another study, the overactivation of the IL-6/JAK/STAT3 pathway was found to promote tumor proliferation and invasion while suppressing anti-tumor immune responses." (PMID 37874419, 2023). "In an NCI-H1703 mouse model, miconazole significantly suppressed tumor size, decreasing the phosphorylation of STAT3 Y705 and the expression of its targets, such as cyclin D1, survivin, and snail." (PMID 37121974, 2023). "Compared with the neutrophils from RM1-derived tumors, the neutrophils in hybrid cell group showed an increased level of Il6/Jak/Stat3 signaling pathway which is usually hyperactivated in tumor infiltrating immune cells to inhibit antitumor immunity." (PMID 37138326, 2023). "The silencing of STAT3 alone also inhibited tumor growth, but the effect was less than simultaneous treatment with STAT3 shRNA and paclitaxel." (PMID 38067351, 2023). "STAT1 plays a distinct role with STAT3 in IL-11-mediated osteoclastogenesis in the tumor microenvironment." (PMID 36593458, 2023). "Activation of STAT3 has tumour promoting effects via suppression of apoptosis and tumour suppressors and induction of proliferation." (PMID 37173424, 2023). "Knockdown of STAT3 in ES cells significantly suppressed ES growth, and public functional genomics data also indicated tumor dependency of STAT3 in ES cells." (PMID 37759224, 2023). "LncRNA VCAN-AS1 has been reported to promote the malignant tumor behaviors via modulating the miR-106a-5p-involved STAT3/HIF-1α axis in breast cancer." (PMID 37696973, 2023). "Several studies indicate that B7-H3 overexpression inhibits the apoptosis of tumor cells via inadequate activation of the JAK2/STAT3 pathway." (PMID 37110590, 2023). "The impacts of the low-toxic compound with phosphorylated-STAT3 (pSTAT3) inhibiting properties, K1836, on tumour cell proliferation, as well as on the SASP of senescent cells were evaluated." (PMID 36825563, 2023). "STAT3 has been long considered a promising drug target due to its involvement in proliferation of tumor cells, inflammation, and immune responses." (PMID 37182134, 2023). "A study by Vangalaet al. revealed that PSMB5 is a target of STAT3 that has been tested in other tumor cells." (PMID 38009004, 2023). "The study also sheds light on the molecular mechanisms involved in MTC metastasis, highlighting the crucial roles of RET, Egr-1 and STAT3 in tumor proliferation, invasion, and angiogenesis." (PMID 37046823, 2023). "In particular, we previously reported the development of SC144, a small-molecule gp130 inhibitor that can block IL-6-induced nuclear translocation of STAT3, and shown their anti-tumor efficacy in murine xenograft tumor models." (PMID 37553327, 2023). "The number of invading cells, indicated by Zeb1+ cells infiltrating outside the gross tumor mass, was significantly reduced by STAT3 or SRF knockdown." (PMID 37558923, 2023). "An upstream regulatory factor MYC and STAT3 are constitutively activated in many cancers and plays a pivotal role in tumor growth and metastasis by regulating cell proliferation, invasion, migration, and angiogenesis." (PMID 36845724, 2023). "Our data confirm that the tumor inflammatory microenvironment in vivo abnormally activates the Stat3/HIF-1α/BNIP3 signaling pathway in skeletal muscle, leading to excessive mitophagy, which disrupts the body's energy balance and ultimately leads to fatigue." (PMID 36814560, 2023). "STAT3 plays a dominant role in negatively regulating the immune response, as well as governing cell growth, differentiation, apoptosis, and tumor development and metastasis." (PMID 37762066, 2023). "It contributes positively to tumor growth and promotion (STAT3 in cancer cells), angiogenesis, tumor escape, and metastasis." (PMID 36835413, 2023).
tumor (continued). "Since the connection between inflammation and tumor development, for example, through inflammation-induced initiating of oncogenic transformation by recruiting immune cells, has become known, attention in tumor research has also fallen on STAT3." (PMID 37140667, 2023). "STAT3 has been shown to have profound effects on tumor progression through its effects on the immune system and the tumor itself." (PMID 37173951, 2023). "Increasing evidence shows that aberrant activation of STAT3 is involved in the proliferation and survival of tumor cells." (PMID 37724127, 2023). "During tumor progression, IL-25 primarily promotes the proliferation and metastasis of tumor cells by activating various signaling pathways, including NF-κB and STAT3." (PMID 37005677, 2023). "More importantly, STAT3 has been connected to induced chemo- and radioresistance in various tumor types." (PMID 37173951, 2023). "IL-11 also participates in tumor initiation and progression by regulating epithelial cell turnover and the IL-11/gp130/STAT3 signaling pathway." (PMID 38352248, 2023). "During tumor progression, STAT3-dependent SERPINA3 enhances tumor cell invasion, migration, and angiogenesis." (PMID 37313408, 2023). "STAT3 is a key oncogene and an important tumor target, and scholars have carried out a considerable amount of research to develop STAT3 inhibitors." (PMID 38031104, 2023). "Reactive astrocytes in the GBM compartment produce tumor-promoting factors such as TGFβ and STAT3 that promote tumor metastasis." (PMID 37304294, 2023). "Our studies further demonstrated the effect of CDK1 in the maintenance of tumor stemness by mediating the phosphorylation of the important transcription factor STAT3." (PMID 37743465, 2023). "In particular, key genes previously associated with the biology of ALCL including STAT3 were expressed in both the PDX and primary tumour." (PMID 37357529, 2023). "Generally, SHP-1-mediated inhibition of the JAK/STAT3 pathway is inversely correlated with tumor progression, aggressiveness, and metastasis." (PMID 38203502, 2023). "In summary, this study explores the oncosuppressive function of TRIM29 in ESCC and reveals that TRIM29 downregulation due to hypermethylation of its promoter, positively regulates tumor suppresser gene ZNF750 via modulating IL6/STAT3 signaling pathway." (PMID 37365152, 2023). "Visfatin induces a G1-to-S cell cycle transition by activating tumor survival signaling pathways such as NF-κB/Notch1, c-Abl/STAT3 and AKT/ERK1/2." (PMID 36765683, 2023). "It mechanically inhibited tumor growth through the VEGFR2/STAT3 pathway and stimulation of pyroptosis." (PMID 37752941, 2023). "It is suggested that degranulation of mast cells initiated via the PAI-1/LRP1/STAT3 axis leads to release of additional chemokines that trigger tumor infiltration of other immune cells and tumor progression." (PMID 38275375, 2023). "In contrast to STAT1, STAT3 is generally described to have tumor-promoting properties, as it regulates the expression of genes involved in cell proliferation, apoptosis, and metastasis." (PMID 37561163, 2023). "The STAT3 signalling promotes tumour growth through the regulation of pro-angiogenic genes, which is echoed by our findings that angiogenesis was significantly enhanced in fatty grafts post liver transplantation." (PMID 37916155, 2023). "A-FABP released from adipose tissue directly targets BCCs and enhances tumor aggressiveness in vivo by activating the IL-6/STAT3/ALDH1 pathway." (PMID 36880535, 2023). "Not only that, PDLIM2 also promotes the degradation of NF-κB and STAT3 and inhibits the development of tumor resistance." (PMID 37894409, 2023). "The Western blot results further confirmed that the expressions of HIF1α, VEGFA, and p-STAT3 were all reduced in the tumor tissue of the shSHMT2 group." (PMID 37108312, 2023).